APOA1 (apolipoprotein A1)
Diseases named in the same sentence as APOA1 in open-access papers (continued):
Sharing a sentence is not in itself a finding about the gene and the disease.
bladder cancer (27 papers, 2011 to 2025). "A prospective hospital-based case-control study was conducted to evaluate the association of the APOA1 −75 G/A and +83 C/T genotypes with predisposition to bladder cancer." (PMID 34440141, 2021). "The results from our study seem to associate the ApoA-1 expression with a lower intensity of bladder cancer, revealing a protective effect." (PMID 34440141, 2021). "Furthermore, apolipoprotein A1 (ApoA1), a protein involved in lipid metabolism, has shown diagnostic promise in distinguishing bladder cancer from other diseases." (PMID 40282460, 2025). "On the other hand, the APOA1 +83 heterozygous genotype CT frequency was seen more in the cases compared with the controls (50% vs. 33%, respectively), and showed a significant association to confer more than a two-fold risk for bladder cancer." (PMID 34440141, 2021). "Our study is the first one to identify the APOA1 protein expression in the urine samples of patients with bladder cancer, and to find out the potential relationship between differentially expressed urinary proteins with different sequence variants of in the APOA1 −75 G/A and +83 C/T genotypes." (PMID 34440141, 2021). "To substantiate whether APOA1 −75 G/A and +83 C/T polymorphic variants could confer a synergistic effect in the development or progression of bladder cancer, we explored their cumulative impact so as to observe their predisposition to the disease." (PMID 34440141, 2021). "The APOA1 gene −75 AA variant, in concordance with its corresponding relation to the urinary APOA1 protein expression, revealed its possible role as a marker for the risk assessment of disease in bladder cancer." (PMID 34440141, 2021). "Therefore, APOA1-75 AA variants in combination with ApoA1 expression may act as a valuable tool to evaluate the malignant degree of bladder cancer." (PMID 36506554, 2022). "In addition, it is showed that the genetic variants of APOA1 are associated with bladder cancer." (PMID 36506554, 2022). "Keeping in mind the plausible role of APOA1 in various malignancies, a combined genetic and proteomic analysis of APOA1 is hypothesized to help observe the predisposition to bladder cancer and may aid in the clinical diagnostic stratification of bladder cancer." (PMID 34440141, 2021). "It was found in high amounts in urine from patients with bladder cancer, and utilizing exfoliative urinary cytology in combination with APOA1 detection increased the sensitivity of diagnosis." (PMID 36812479, 2023). "It is reported that the elevated level of ApoA1 in urine can facilitate the diagnosis of patients with bladder cancer, which shows high sensitivity and specificity." (PMID 36506554, 2022). "The APOA1 protein was further tested quantitatively by ELISA so as to measure its differential expression pattern in order to distinguish the patients with bladder cancer of varied pathologies." (PMID 34440141, 2021). "Among the different stages of bladder cancer, ApoA-1 showeda lower expression (<20 ng/mL) with each subsequent higher stage, namely Ta (47.6%), T1 (52.3%), and T2 (70%)." (PMID 34440141, 2021). "For instance, a negative pressure-driven microchip integrating magnetic microbead-assisted immunocapture of bladder cancer biomarker apolipoprotein A1 (APOA1), report a measurement time of 40 min which is six times faster than a conventional ELISA test." (PMID 32521780, 2020). "Over-expression of APOA1 has also been observed in bladder cancer and aggressive bladder transitional cell carcinoma." (PMID 26463353, 2016). "Furthermore, urinary ApoA1 in low-grade bladder cancer cases shows a high expression, while patients with high-grade bladder cancer are more likely to have a low urinary ApoA1 expression." (PMID 36506554, 2022). "The urine level of ApoA1 and ApoA2 also have the potential for predicting bladder cancer." (PMID 36506554, 2022). "Specifically, bladder cancer cases with APOA1-75 AA genotype reveal a high ApoA1 level in urine." (PMID 36506554, 2022).
bladder cancer (continued). "The concentration levels of the three circulating proteins inversin, gelsolin, and apolipoprotein A1 identified high-grade bladder cancer with an AUC > 0.84 (95% confidence interval 71–98), 0.76 (95% confidence interval 61–92%), and 0.90 (95% confidence interval 82–98), respectively." (PMID 34947825, 2021). "Recently, APOA1 −75 G/A and +83 C/T have been observed to have strong relation to renal tumors, and their protein expressions have been demonstrated to be potential biomarkers in bladder cancer." (PMID 34440141, 2021). "In addition, we investigated the APOA1 protein expression in the urine samples of patients with bladder cancer in order to find the potential relationship between differentially expressed urinary proteins and variations in the APOA1 genotypes." (PMID 34440141, 2021). "Some of the proteins such as SERPINA1, FGG, FGA, APOA1 and HP were also found with differential abundance in urine in proteomics studies of bladder cancer, and TYMP in tissue in renal cell carcinoma, but mostly with opposite abundance level compared to our study." (PMID 25653573, 2015). "Moreover, our study gives evidence of the vital role of APOA-1 in carcinogenesis at genetic and protein levels, and augments further functional studies that can provide additional inputs in the patho-physiological course on different cancers, in particular bladder cancer." (PMID 34440141, 2021). "The same research group found that the urinary APOA1 and APOA2 levels in bladder cancer samples were higher than the levels established in control samples." (PMID 30544619, 2018). "Circulating urine levels of APOA1, APOA2, APOB, APOC2, APOC3, and APOE were elevated in bladder cancer relative to healthy controls." (PMID 28410618, 2017). "Several independent studies support the utility of circulating AQ1 and APOA1/APOA2 as non-invasive markers for RCC and bladder cancer, respectively." (PMID 28410618, 2017). "The authors report elevated levels of SAA4, ProEGF, and six apolipoproteins (APOA1, APOA2, APOB, APOC2, APOC3, and APOE) in patients with bladder cancer." (PMID 27119500, 2016). "Two independent studies report elevated levels of urinary APOA1 and APOA2 in bladder cancer." (PMID 27119500, 2016). "We observed increased expression of five proteins, including fibrinogen (Fb), lactate dehydrogenase B (LDHB), apolipoprotein-A1 (Apo-A1), clusterin (CLU) and haptoglobin (Hp), which were increased in urine samples of patients with low malignant or aggressive bladder cancer." (PMID 21496341, 2011).
Hepatic steatosis (27 papers, 2016 to 2026). Steatosis is a term used to denote lipid accumulation within hepatocytes. "This study demonstrates that OA induces hepatic steatosis in duck hepatocytes by upregulating APOA1, an effect associated with the activation of the PPAR signaling pathway." (PMID 41463887, 2025). "Liver enzyme activity (ALT, AST, GGT), total bilirubin, lipids fractions, apolipoprotein A1 (ApoA1), α-2-macroglobulin (α2M), haptoglobin (Hp), fasting blood glucose, and fasting insulin are used to generate liver steatosis scores." (PMID 35268466, 2022). "After adjustment for age and gender (Model 1) and for age, gender, glucose, triglycerides, apoA1, apoB100, and AST (Model 2), the associations between FABP4 and liver steatosis were significant in all the studied groups, including obese patients." (PMID 34966292, 2021). "Notably, the triglyceride-to-APOA1 ratio has recently emerged as a promising biomarker for human hepatic steatosis." (PMID 41463887, 2025). "One research demonstrated the protective role of ApoA1 in a diet-induced fatty liver animal model." (PMID 34007294, 2021). "Apolipoprotein A1 (APOA1) is involved in regulating both lipid and energy metabolism, which may play important roles in liver regeneration, especially in cases of liver steatosis." (PMID 31680967, 2019). "This is mainly the reason why up to 40% of dairy cows develop fatty liver disease and could explain as well such an increased amount of ApoA-1 in adipose tissue." (PMID 31766506, 2019). "In participants with severe hepatic steatosis (n = 43), subgroup analysis showed increased COL18A1, AFM, PRG4, and INHBE and decreased C4A and APOA1." (PMID 41354933, 2025). "Lipoproteins are composed of lipids, cholesterol and apolipoproteins, and the expression of apolipoproteins A1, A4 and C3 (APOA1, APOA4 and APOC3) increased significantly in the hepatic steatosis groups, suggesting an increased level of cholesterol transport." (PMID 37568219, 2023).
pancreatic cancer (27 papers, 2011 to 2025). "The degradation of APOA1 enhances the lipid anabolism of pancreatic cancer cells and promotes the accumulation of lipid droplets." (PMID 39944823, 2025). "A downregulation of APOA1 has been observed in the serum of patients with several malignancies, indicating unfavorable prognosis, including ovarian, breast, and pancreatic cancers." (PMID 39194522, 2024). "Downregulating the expression of TRIM15 led to increasing the levels of APOA1, which was found to suppress the metastasis of pancreatic cancer." (PMID 38067270, 2023). "We previously reported that TRIM15 promotes APOA1 ubiquitination and degradation in pancreatic cancer." (PMID 36670097, 2023). "We previously reported that TRIM15 targets APOA1 for degradation to promote the malignant progression of pancreatic cancer cells." (PMID 36670097, 2023). "Here, we observed high SAA1 levels and a reduction of the APOA1-to-SAA1 plasma ratio in patients with pancreatic cancer." (PMID 35577388, 2022). "APOA1 has been identified as a potential biomarker of ovarian, colorectal, hepatocellular, and pancreatic cancer." (PMID 34440141, 2021). "APOA1 was found to be highly expressed in tumor tissue compared to non-tumor tissue, suggesting its potential use as a sensitive and specific marker for early-stage pancreatic neoplasms." (PMID 38067270, 2023). "Interestingly, plasma samples from pancreatic-cancer patients displayed a significantly reduced APOA1-to-SAA1 ratio and a reduced cholesterol efflux capacity compared with healthy donors." (PMID 35577388, 2022). "Additionally, TRIM15 promotes the invasion and metastasis of pancreatic cancer cells by mediating APOA1 ubiquitination and degradation." (PMID 35534896, 2022). "Interestingly, SAA1, an acute phase protein that associates with and potentially decreases the efflux capacity of HDL particles, was highly enriched in plasma samples of pancreatic-cancer patients, thereby reducing the APOA1-to-SAA1 ratio in those patients." (PMID 35577388, 2022). "In addition, we found that TRIM15 might be involved in the regulation of lipolysis in adipocytes, which was consistent with our previous finding that TRIM15 targets APOA1 for degradation in pancreatic cancer." (PMID 36670097, 2023). "In pancreatic ductal adenocarcinoma, ubiquitination and degradation of ApoA1 mediated by TRIM15 can promote the invasion and metastasis of pancreatic cancer cells." (PMID 38212711, 2024). "Using advanced mass spectrometry-based techniques, it was shown that using a panel of APOA1, APOE, APOL1, and trypsin inhibitor heavy chain H3 (ITIH3) can provide a sensitivity of 95% and specificity of 94.1% in the diagnosis of pancreatic cancer." (PMID 38067270, 2023). "Consistently, ITIH3, which has significant involvement in extracellular matrix remodeling during tumor progression, along with APOA1, APOE, APOL1, and CA19-9, constitutes a biomarker panel for pancreatic cancer." (PMID 37628784, 2023). "TRIM15 interacts with APOA1 through its PRY/SPRY domain, and mediates the ubiquitination and degradation of APOA1 dependent on its RING domain, thereby promoting the invasion and metastasis of pancreatic cancer cells." (PMID 36249749, 2022). "TRIM15 could regulate the Wnt/β-catenin signaling pathway and Keap1-Nrf2 pathway and mediate the ubiquitination of APOA1 and ERK to promote the development and progression of cancers such as non-small cell lung cancer, esophageal squamous cell carcinoma, and pancreatic cancer." (PMID 36189312, 2022).
cognitive decline (26 papers, 2012 to 2025). "This is supported by several studies indicating that lower plasma levels of apolipoprotein A1 (ApoA1) are associated with cognitive decline in specific populations." (PMID 40875171, 2025). "An association between serum apolipoprotein A1 and cognitive decline has been suggested in subjects with low brain amyloid-beta burden." (PMID 38167163, 2024). "Pillai JA found that higher plasma apolipoprotein A1 was associated with faster cognitive decline in mild cognitive impairment." (PMID 38167163, 2024). "A previous retrospective longitudinal study with 156 participants showed that higher ApoA1 was associated with faster cognitive decline in AD patients, which is inconsistent with our results." (PMID 39583797, 2024). "In the Sydney Memory and Aging Study, a lower ApoA1 level and higher ApoB/ApoA1 ratio were associated with a greater risk of cognitive decline." (PMID 36247924, 2022). "Previous research has shown a higher ApoB/ApoA1 ratio indicates a higher risk of cognitive decline in the future." (PMID 39484667, 2022). "Whilst increased plasma ApoA-1 in association with cognitive decline and brain atrophy have been observed." (PMID 30618716, 2018). "In summary, participants with lower ApoA1, ApoA2, ApoH levels or higher ApoB/ApoA1, at Wave 1 had a higher risk of future cognitive decline." (PMID 22701550, 2012). "Lower ApoA1, ApoA2 and ApoH levels, and higher ApoB/ApoA1 ratio, increased the risk of cognitive decline over two years in cognitively normal individuals." (PMID 22701550, 2012). "Higher plasma ApoA1 was associated with faster decline in MMSE and LM among MCI, while in contrast higher CSF ApoA1 levels related to slower cognitive decline in MMSE among MCI." (PMID 36927447, 2023). "In blood analysis, the CGA group showed increased levels of apolipoprotein A1 and transthyretin, both of which are putative biomarkers for early-stage cognitive decline." (PMID 30241302, 2018). "In this study, ApoA1 concentration was lower in MCI, and a low level of ApoA1 was the strongest risk factor of cognitive decline in comparison with other apolipoproteins." (PMID 22701550, 2012). "Interestingly, the same study revealed that higher cerebrospinal fluid ApoA1 level was related to slower cognitive decline in the same cohort." (PMID 39583797, 2024). "Blood concentrations of TTR and ApoA1—proteins whose reduced levels are markers of early-stage cognitive decline—increased after the CGA treatment, which might reflect the improved cognitive functions observed in the neuropsychological tests." (PMID 30241302, 2018). "Only ApoA1 showed a statistically significant effect on cognitive decline from CDR = 0 to CDR >0 after controlling for the effects of the other apolipoproteins, and also age, sex, years of education, APOEε4 carrier status and CVD risk index (OR = 0.63, 95%CI = 0.48–0.84, P = 0.001)." (PMID 22701550, 2012). "Mounting evidence highlights the potential of metabolic biomarkers, including triglyceride/HDL ratios, ApoA1 levels, and glucose metabolism patterns, on PET scans as predictive tools for cognitive decline." (PMID 40137124, 2025). "This study highlighted the significant associations between PD-MCI and several factors, including triglycerides (TG), apolipoprotein A1 (ApoA1), and the SNCA rs6826785 genetic marker, suggesting their potential role in early cognitive decline in PD patients." (PMID 39767666, 2024). "The role of peripheral and cerebrospinal fluid (CSF) levels of Apolipoprotein A1 (ApoA1), a key functional component of HDL, on cognitive decline also remains unclear among them." (PMID 36927447, 2023). "Plasma levels of ApoA1 and the TG/HDL-C ratio appear to be promising prognostic markers for the rate of cognitive decline in MCI and AD dementia subjects and their therapeutic modification by diet and medication options in these clinical subjects is likely to be of high future interest." (PMID 36927447, 2023).
cognitive decline (continued). "ApoA1, ApoH and ApoJ are potential plasma biomarkers of cognitive decline in non-demented elderly individuals." (PMID 22701550, 2012).
coronary atherosclerosis (25 papers, 2009 to 2025). Atherosclerosis of the coronary vasculature. "At the same time, atherogenic lipoproteins that have been identified, the high apoliprotein B, low apolipoprotein A-1 and the high ratio of apoB: apoA1 also affect the formation and progression of coronary atherosclerosis." (PMID 30134981, 2018). "Using recombinant apoA1 particles, Nissen and colleagues showed regression of coronary atherosclerosis in patients given 5 weekly intravenous injections, and it is tempting to speculate that the efficacy was due, at least in part, by the mechanisms illustrated by our studies." (PMID 27572261, 2016). "The genetic prediction of the ApoB/ApoA1 ratio was significantly positively correlated with diseases like IHD, coronary atherosclerosis, angina pectoris, unstable angina pectoris, and MI." (PMID 38310324, 2024). "However, considering the potential value of ApoB/ApoA1 ratio in predicting IHD, our study analyzed its common representative diseases, such as coronary atherosclerosis, angina pectoris and ACS (including unstable angina pectoris and MI)." (PMID 38310324, 2024). "However, we must be cautious not to draw too far-reaching conclusions as some human clinical trials demonstrated that increased levels of HDL-C and ApoA1 do not always reduce coronary atherosclerosis progression." (PMID 37686357, 2023).